C1orf94 (chromosome 1 open reading frame 94)
Synonyms: MGC15882
Tractability: No criterion of Open Targets' tractability assessment is met for any kind of drug.
Gene: Protein-coding gene on chromosome 1 (34,166,883 to 34,219,131, forward strand). Ensembl gene ENSG00000142698.
Subcellular location (Human Protein Atlas): Cytosol; Nucleoplasm
Gene Ontology:
Molecular function: protein binding
Genetic constraint (gnomAD): Loss-of-function variants: 45 observed, 56.46 expected, observed/expected ratio (o/e) 0.8, 90% interval 0.63 to 1.02. The upper end of that interval is the gene's LOEUF score, 1.02, which puts it in group 4 of 6, group 1 being the genes least tolerant of losing a copy. Missense variants: 762 observed, 776.65 expected, observed/expected ratio (o/e) 0.98, 90% interval 0.92 to 1.04. Synonymous variants: 304 observed, 308.94 expected, observed/expected ratio (o/e) 0.98, 90% interval 0.89 to 1.08.
Homologues: Orthologues: chimpanzee C1H1orf94 (97% identical), macaque C1H1orf94 (94% identical), pig C1orf94 (78% identical), rabbit C1orf94 (75% identical), rat C5h1orf94 (72% identical), mouse CK137956 (72% identical), guinea pig C1orf94 (71% identical), dog C1orf94 (69% identical).